RNU2-63P (RNA, U2 small nuclear 63, pseudogene)
Gene: Small nuclear RNA gene on chromosome 2 (88,016,354 to 88,016,547, reverse strand). Ensembl gene ENSG00000222724.
Homologues: Orthologues: chimpanzee U2 (77% identical), rat LOC120099534 (34% identical), rabbit U2 (32% identical), rabbit U2 (30% identical), tropical clawed frog U2 (28% identical), dog U2 (24% identical), tropical clawed frog U2 (16% identical). Paralogues in human: U2 (70% identical), RNU2-2 (70% identical), RNU2-36P (69% identical), RNU2-48P (68% identical), RNU2-4P (68% identical), RNU2-59P (68% identical), RNU2-3P (68% identical), RNU2-26P (67% identical), RNU2-64P (67% identical), RNU2-6P (67% identical), RNU2-17P (66% identical), RNU2-57P (66% identical), and 65 more.